NOTCH1 (notch receptor 1)
Diseases named in the same sentence as NOTCH1 in open-access papers (continued):
Sharing a sentence is not in itself a finding about the gene and the disease.
tumor (continued). "For instance, in context to tumor microenvironment (TME), it has been observed that epithelial NOTCH1 signaling drives metastasis in serrated colorectal cancer (CRC), where poor‐prognosis of CRC subtypes CMS4/CRIS‐B are controlled by NOTCH1." (PMID 33822486, 2021). "In addition, pharmacologic activation of both Notch1 and Raf-1 signaling in MTC cells reduces aberrant secretion of hormones and tumor cell proliferation, suggesting a tumor suppressive role for Notch1 signaling in this context." (PMID 33681228, 2021). "In another report, where Notch1 was found to induce pro-tumor activities in luminal-A BC cells and in the non-transformed breast epithelial cells in culture, Notch1 was also found to induce p65 activation." (PMID 32605277, 2020). "Additionally, numerous targets of expressions which were observed in carcinogenesis and tumor progression were reported to be regulated by miR-34a, such as CD44, BCL2, NOTCH1, CDK4/6, MET, MYC, and many other molecules." (PMID 32391256, 2020). "In contrast, targeting either the N terminus or C terminus of Notch1 in MK1097-5R tumours did not result in any obvious effects." (PMID 32591500, 2020). "In conclusion, our results indicate that NOTCH1 may be an oncogenic driver for BRCA1-related TNBC and basal-type tumours." (PMID 32591500, 2020). "Notch1 and Notch2 were found to be downregulated in tumor infiltrating T cells but not in splenic T cells of tumor-bearing mice." (PMID 32922403, 2020). "No published studies we are aware of have functionally examined the impact of NOTCH1 signaling on cancer stem cell frequency in mouse tumor models in the absence of pre-cultivation as spheroids." (PMID 33322834, 2020). "Blockade of NO synthase could restore the level of Notch1 and Notch2 in T cells as well as eliminate the MDSC-mediated immune suppression to re-establish anti-tumor responses." (PMID 33585446, 2020). "In agreement with previous findings, silencing of the CSL but not NOTCH1 gene in f-HDFs resulted in up-regulation of a number of CAF effector genes with a key tumor-promoting function." (PMID 33046701, 2020). "Because the primary function of Notch1-IC is to activate transcription, consistently activated Notch1-IC promotes tumorigenesis by effectively multiple tumor-promoting pathways in T-ALL." (PMID 33072583, 2020). "Additionally, upon knockdown of Notch1 via short-interfering RNA (siRNA), or inhibition of Notch1 via the bioactive compound Psoralidin, ALDH+ cells were growth inhibited, formed fewer mammospheres, had increased apoptosis, and limited tumor growth in mice." (PMID 33003540, 2020). "In parallel, SOX2 was found to cooperate with important oncogenes, like Wnt1 (OMIM: 164820), Wnt2 (OMIM: 147870), c‐Myc (OMIM: 190080), and Notch1 (OMIM: 190198), to promote lung tumor occurrence, while downregulation of SOX2 inhibited proliferation and induced apoptosis in tumor cells." (PMID 32130794, 2020). "The importance of the NOTCH1/HES1/DLL4/VEGFA/MMP13 axis in cholangiocarcinogenesis was confirmed in a collection of human iCCA tumor patients, paving the path for further investigations into the role of these genes in this tumor type." (PMID 32042099, 2020). "This is illustrated for example by studies on tumor initiation (Notch1; Notch3), stem cell control (Notch1; Notch4; Jag1; Jag2; DLL1), angiogenesis (Notch1; DLL4) invasion and metastasis in remote organs (Notch1; Notch2; Jag1; DLL1)." (PMID 32605277, 2020). "Chronic in vitro NOTCH1 activation in the HNSCC cell line PJ34 actually decreased expression of EMT markers, which was also observed in a second NOTCH1-wt tumor line (manuscript in preparation)." (PMID 33322834, 2020). "Impaired NOTCH1 activity may result in the activation of specific oncogenes (c-MYC, NFkB, or mTOR) or inhibition of tumor suppressor expression (FBXW7, PTEN, CDKN1B)." (PMID 32766158, 2020).
tumor (continued). "Commonly, Notch1 signaling is absent from NETs and its significant tumor suppressor role has been confirmed." (PMID 32496505, 2020). "Adult Group 3 tumours lacked hallmark MYC amplifications, but had recurrent mutations in KBTBD4 and NOTCH1." (PMID 33172502, 2020). "In another series of human PAs, NOTCH 1–4 receptor subtypes, and their ligand JAGGED1 were detected by RT-PCR, suggesting the presence of a constitutive autocrine/paracrine NOTCH system activation in a subset of tumor cells." (PMID 32153500, 2020). "Collectively, the RPPA and Western blot data indicate that roughly two thirds of NOTCH1-wt HNSCC tumor lines have little to no baseline activation of the NOTCH1 pathway." (PMID 33322834, 2020). "Finally, compared to macroH2A1 KD Huh-7 cells, FAK KD cells exhibited a significant reduction (p < 0.01) in the mRNA levels of tumor-promoting genes CCL2, EGF, BAX, KRT19, EGFR, NOTCH1, ABL1, and SMAD3." (PMID 33182805, 2020). "In detail, c-Myc and Notch1 have been identified among the target genes through which FBXW7 influences skin carcinogenesis by counteracting the proliferation-promoting effect of c-MYC and the tumor-suppressive effect of NOTCH1, respectively." (PMID 32560247, 2020). "One of the indications to possible Notch1-mediated increase in malignant features of BC cells through p65 activation was provided by a study demonstrating that Notch1 activation in TNBC cells increased the proliferation, adhesion, invasion and motility of the tumor cells." (PMID 32605277, 2020). "Knockdown of ICN1 blocked the growth of MK1370-3R tumours, whereas targeting endogenous Notch1 did not have a significant effect." (PMID 32591500, 2020). "We identified tumor initial cells (TICs) from a number of ESCC cell lines and demonstrated increased expression of GASC1 in the ESCC ALDH + TICs and its involvement in TICs maintenance by specific demethylation of H3K9Me3 at the SOX2 and NOTCH1 promoter." (PMID 32411232, 2020). "The biological significance of NOTCH signaling in ATL was demonstrated by blockade of NOTCH1 signaling with either dominant negative MALM1 or gamma secretase inhibitor, which significantly reduced ATL tumor growth in vitro and in a xenograft mouse model of ATL." (PMID 32907612, 2020). "Several studies have indicated that miR-34a suppressed the migration and invasion of tumor cells by down-regulating HNF4γ and Notch1, consistent with our hypothesis that DNMT3B may play its role by miR-34a-HNF4γ and/or Notch1 axis." (PMID 33221743, 2020). "This short-term treatment with the anti-Notch1 antibody did not affect cell viability or tumor cell counts (data not shown)." (PMID 31676012, 2019). "Collectively, these results indicate that Notch1-expressing tumour cells are transcriptionally related to normal ISCs." (PMID 30696875, 2019). "Among ADAM17 substrates, IL‐6R, TNFα, Notch1, and EGFR family ligands (e.g., TGFα, amphiregulin, epiregulin, and neuregulin‐1) promote the proliferation, survival, migration, and/or invasion of tumor cells (Zunke & Rose‐John, 2017), thus suggesting a prominent role for ADAM17 in cancer." (PMID 30833304, 2019). "To this end, we have analyzed the expression of CXCL8 in TNFα-stimulated and non-stimulated MDA-MB-231:MSC co-cultures in which Notch1 was down-regulated by siRNA in the tumor cells." (PMID 31105691, 2019).
tumor (continued). "Finally, we observed SMO, LRP, CSKNK2A2, DVL, TEAD, NOTCH1 and KLF4 mutated genes, which are crucial in the regulation of Wnt, Notch and Hedgehog signalling pathways and thus could be the possible culprit behind the enrichment of CSCs in tumour and distal margin." (PMID 30950180, 2019). "Again, the downregulation of Notch1, which occurs as a downstream effect of PrPc silencing, inhibits the PI3K/Akt/mTOR pathway to abolish GSCs’ stemness, self-renewal, invasiveness and in vivo tumor growth." (PMID 31618844, 2019). "The comparison we report between Notch1+ and Lgr5hi tumour signatures indicates that the Wnt pathway is not activated in Notch1+ tumour cells, as compared to normal ISCs." (PMID 30696875, 2019). "Protein extracts were obtained and Western Blot analysis confirmed that OMP-52M51 was able to inhibit cleaved Notch1 in vivo, although this short-term OMP-52M51 treatment was not enough to cause a significant efficacy in tumor growth." (PMID 31676012, 2019). "Our finding showed that NOTCH1 and DLL1 are both highly expressed in tumor cells." (PMID 31118022, 2019). "The down regulated proteins were associated with genome instability (plasmamix Histon H3 (diMeth K9), Histone H3), the regulation of tumour growth (Androgen receptor, beta-catenin, Bim, Shh), DNA repair (PARP-1) and Notch signaling (Notch 1 intracellular domain (N1ICD), RBPSUH)." (PMID 31758038, 2019). "The novel putative intestinal and pancreatic stem cell marker DCAMKL-1, a microtubule-associated kinase, plays a key role in tumorigenesis by downregulating tumor suppressor microRNAs thus inducing tumor promoters specific targets such as ZEB1, ZEB2, and Notch-1." (PMID 31861725, 2019). "Next, we defined the genome-wide transcriptional signature of Notch1+ tumour cells and normal ISCs by performing Affymetrix analyses of FAC-sorted GFP+ and GFP- tumour and normal crypt cells derived from N1-Cre/R26mTmG/Apc and N1-Cre/R26mTmG mice, respectively." (PMID 30696875, 2019). "Spinal metastases expressed higher levels of NOTCH1 and Notch1 pathway-regulated genes (including genes responsible for motility, migration, and adhesion, such as TWIST1) compared to primary tumor sites, suggesting a distinct population of MB cells that are able to metastasize." (PMID 30876441, 2019). "Indeed, the inhibition of Slug/Notch1 signaling axis, by regulating EMT process, seems to be sufficient to decrease tumor-initiating cells (TICs) number, tumor induction, and metastasis." (PMID 31379945, 2019). "Notch1+ tumour cells (GFP+) also showed enriched expression in reported markers of ISCs, such as Hopx2, Musashi122 (Msi1) and Bmi17 compared to GFP-epithelial cells within the same tumours." (PMID 30696875, 2019). "In addition, Notch1 can reduce the expression of zinc finger E-box binding homeobox (ZEB) and vimentin by regulating miR-200b, thereby promoting tumor cell EMT." (PMID 30622441, 2019). "Similar results were observed following IL-1β stimulation, demonstrating that 7-h stimulation, but not 15-min stimulation by IL-1β has led to Notch1 activation in the tumor cells, but not in the MSCs." (PMID 31105691, 2019). "Here, the active form of Notch1 is expressed in extra-tumoral lymphatic endothelial cells together with a receptor of VEGF-C, VEGFR3, involved in lymphatic endothelial cell proliferation, tumor lymphatic invasion, and tumor metastasis." (PMID 30154786, 2018). "We found that the mRNA levels of Notch1 were higher in GBM than in non-neoplastic brain tissues, indicating that Notch1 acted as a tumor promoter in GBM." (PMID 29410396, 2018). "Furthermore, Notch1 inhibited CD8+ cytotoxic T lymphocytes infiltration and IFN-γ release in tumor tissues." (PMID 29301578, 2018). "In summary, the present study demonstrates that LGR5 is overexpressed in EOC tumor samples and that dysregulated LGR5 expression, which occurs frequently in EOC, promotes tumor proliferation, metastasis, and EMT of EOC cells through the Notch1 signaling pathway." (PMID 29777575, 2018).
tumor (continued). "Clinical data has shown higher Notch1 activation in tumor endothelial cells compared to non-malignant tissue." (PMID 30515368, 2018). "Thus, the regulation of FBW7 is expected to exhibit anti-metastatic function through the regulation of the interaction between Notch-1 and CCL2 in tumor stroma composed of F4/F80-positive TAMs and Ly6C-positive MDSCs." (PMID 30053872, 2018). "In addition to reducing NOTCH1/2 levels, reductions in NOTCH ligand expression on T-cells and other immune cells has also been observed in murine tumor models." (PMID 30967879, 2018). "In addition, Notch1 plays as a fundamental regulator in the induction as well as the maintenance of EMT and tumor progression." (PMID 29321718, 2018). "The reason why elevated Notch1 ICD levels specifically led to a decrease in tumor growth from DAOY-NERT2HIF2α−/− cells but not from DAOY-NERT2HIF2α+/+ control cells is not understood." (PMID 29993038, 2018). "In this study, DLD-1R and HCT-116R cells appeared to be sensitive towards regorafenib treatment as demonstrated by the decreased number of colonies, tumor spheres and stem-like phenotypes (tumor spheres and side-populations) and markers (WNT1, mTOR/STAT3, Notch1)." (PMID 30005681, 2018). "In in vitro cytotoxicity assay, knocking down Notch1 significantly increased the CTL activity in tumor-DLNs but not in spleens." (PMID 29301578, 2018). "On the other hand, several studies reported that high NOTCH1 and NOTCH2 expression with early tumor stages might indicate a tumor-suppressive role of NOTCH signaling in gastric cancer." (PMID 29665790, 2018). "Furthermore the invasiveness of the tumor and hypoxia induced EMT requires Notch1 signaling, demonstrating a hypoxia/Notch1/EMT axis." (PMID 30515368, 2018). "Furthermore, the expression of stemness genes ABCG2, Nanog, Notch1 and Oct4 as well as Wnt-related genes CCND1, c-Jun, VEGF, and c-myc in tumor xenografts was down-regulated in shRab37 + rSFRP1 group (symbols pink vs. red)." (PMID 30158579, 2018). "Although the mechanism by which Akt activity is influenced by Notch1 has not been fully elucidated, existing data indicate that Notch1 stimulates Akt activation through suppressing Pten, a renowned tumor suppressor." (PMID 29636838, 2018). "MiR-101 acts as a tumor suppressor through the repression of proliferation and invasion, induction of apoptosis, and enhancement of chemotherapeutic sensitivity in T-ALL cells in vitro mediated by inhibiting NOTCH1." (PMID 29435192, 2018). "Nevertheless, it is important to note that in the majority of CRC cases analyzed in the present study, both POFUT1 and NOTCH1 are overexpressed (60.5%), suggesting that overexpression of POFUT1 is necessary to ensure O-fucosylation of additional NOTCH receptors in the tumor." (PMID 30380753, 2018). "Our study showed that PDGF-D was highly expressed in CRC tissues and it could promote tumor growth, invasion, angiogenesis, and EMT transformation by activating Notch1/Twist1 axis." (PMID 28035069, 2017). "In addition, DCLK1 also regulates Notch-1 via a miR-144 dependent mechanism and its downstream effector HES1 to promote tumor xenograft growth." (PMID 29246000, 2017). "Significant difference of Notch1 and Hes1 were observed between tumor and non-tumor tissues (P<0.001)." (PMID 27705934, 2017). "Although the importance of gal-3 in angiogenesis is already widely appreciated, we now point to a novel regulatory mechanism by which tumor-secreted gal-3 increases tip cell formation and sprouting angiogenesis because of its ability to upregulate JAG1/Notch-1 signaling in endothelial cells." (PMID 28533486, 2017).
tumor (continued). "Notwithstanding, genetic alterations that activate neurogenic locus notch homolog protein 1 (NOTCH1) signaling and T-cell transcription factors, coupled with inactivation of the inhibitors of CDK4/alternate reading frame (INK4/ARF) tumor suppressors, are hallmarks of T-ALL." (PMID 28872614, 2017). "Overall, the current data show multiple targets of ZR30 for its tumor suppressive effect, including membrane receptors (EGFR, NOTCH1) and their downstream AKT-signaling, pro-invasive and pro-angiogenic extracellular protease (MMP2), and oncogenic transcription factor (FOXM1)." (PMID 29290950, 2017). "In this study, GC progression was inhibited by luteolin through suppressing Notch1 signaling and reversing EMT, suggesting that luteolin may serve as an effective anti-tumor drug in GC treatment." (PMID 28241766, 2017). "Our results revealed the tumor-suppressive character of KMT2A, NOTCH1, and NOTCH3 in U-87 MG cells." (PMID 28968975, 2017). "The Multiple Beam Search (MBS) algorithm learned interactions from data and discovered that hsa-miR-21, hsa-miR-10b, hsa-miR-448, and hsa-miR-96 interact with oncogenes, such as, CCND2, ESR1, MET, NOTCH1, TGFBR2 and TGFB1 that promote tumor metastasis, invasion, and cell proliferation." (PMID 28793339, 2017). "We found that Notch1 expression was correlated with formation of vasculogenic mimicry (VM) and expression of biomarkers of epithelial-to-mesenchymal transition (EMT) in the tumor specimens." (PMID 27705934, 2017). "While purified CD44H cells were highly tumorigenic (80–100%), neither ectopic ICN1 nor DNMAML1 affected tumor initiation by CD44H cells, suggesting that established CD44H-mediated tumor initiation is independent of Notch1." (PMID 29170450, 2017). "CSMD1, CDKN2A, NOTCH1, and SMAD4 are known to be tumor-suppressor genes." (PMID 29340043, 2017). "The mRNA levels of Notch1 and Jagged1 were either unchanged or even decreased in tumor lesions compared to the non-tumor lesions." (PMID 26766040, 2016). "We previously demonstrated NOTCH1 downregulation in cancer cells in OSCC by microarray and immunohistochemical studies using human OSCC samples, and recent studies have indicated that NOTCH1 acts as a tumor suppressor in OSCC pathogenesis." (PMID 27124156, 2016). "To confirm whether the tumor decrease was directly correlated with CSC blockade, we compared the molecular expression of NOTCH1 and HES1 in 10 mg/kg or vehicle group xenograft mice using Western blot and immunohistochemistry." (PMID 27108536, 2016). "This study found Notch1, Notch2, and Notch4 to be involved in stromal-dependent CLL resistance to fludarabine and cyclophosphamide chemotherapy, with mesenchymal stem cells dramatically increasing tumor cell survival." (PMID 26934331, 2016). "Indeed, among the genes induced by Notch1 in cells and up-regulated in tumors with high Notch1 levels, besides the Notch1 target HES1, we found many genes with tumor-promoting functions." (PMID 27384993, 2016). "Results support Notch1′s putative tumour progression function, but there is little evidence of associated downstream factors that contribute to the regulation of these processes associated with HOTAIR." (PMID 27323817, 2016). "RNA-FISH analysis showed that neither TUG1 nor Notch1-positive cells were observed in residual tumours in mice with TUG1-DDS treatment, whereas in mice with CTRL-DDS treatment, TUG1 and Notch1 expression was predominantly observed in the perivascular regions." (PMID 27922002, 2016). "Notably, in tumor settings, down-regulation of PDGF-D has been shown to decrease expression of Notch-1." (PMID 27032083, 2016). "We focused on Notch signaling because direct overexpression of the Notch1 ICN initiated CCA tumor growth in the murine liver without known genetic alterations." (PMID 26954680, 2016).